CDHR4 (cadherin related family member 4)
Description:
Cadherins are calcium-dependent cell adhesion proteins. They preferentially interact with themselves in a homophilic manner in connecting cells; cadherins may thus contribute to the sorting of heterogeneous cell types (By similarity).
Synonyms: CDH29; VLLR9392; PRO34300
Tractability: Antibody: UniProt predicts a signal peptide or a membrane-spanning region; its Gene Ontology location is reachable by antibodies, with medium confidence.
Gene: Protein-coding gene on chromosome 3 (49,790,732 to 49,799,873, reverse strand). Ensembl gene ENSG00000187492.
Subcellular location: Membrane
Gene Ontology:
Molecular function: cell adhesion molecule binding; calcium ion binding
Biological process: cell adhesion; homophilic cell-cell adhesion
Cellular component: plasma membrane; membrane
Genetic constraint (gnomAD): Loss-of-function variants: 89 observed, 90.39 expected, observed/expected ratio (o/e) 0.98, 90% interval 0.83 to 1.17. The upper end of that interval is the gene's LOEUF score, 1.17, which puts it in group 5 of 6, group 1 being the genes least tolerant of losing a copy. Missense variants: 914 observed, 1,039.9 expected, observed/expected ratio (o/e) 0.88, 90% interval 0.83 to 0.93. Synonymous variants: 368 observed, 414.22 expected, observed/expected ratio (o/e) 0.89, 90% interval 0.81 to 0.97.
Homologues: Orthologues: chimpanzee CDHR4 (98% identical), pig CDHR4 (79% identical), rabbit CDHR4 (77% identical), mouse Cdhr4 (72% identical), rat Cdhr4 (71% identical), tropical clawed frog CDHR4 (37% identical). Paralogues in human: PCDHB7 (22% identical), PCDHB15 (22% identical), PCDHB4 (22% identical), PCDHGA1 (22% identical), PCDHB5 (22% identical), PCDHB6 (22% identical), PCDHGA6 (22% identical), PCDHB11 (22% identical), PCDHB12 (22% identical), PCDHB9 (22% identical), PCDHGA2 (22% identical), PCDHGA9 (22% identical), and 49 more.
Diseases named in the same sentence as CDHR4 in open-access papers:
CDHR4 is named in the same sentence as 1 disease in open-access papers, as found by Europe PMC text mining. Sharing a sentence is not in itself a finding about the gene and the disease.
CDHR4 shares sentences with these, for which no sentence is quoted: tumor (1 paper).